ABCG2 (ATP binding cassette subfamily G member 2 (JR blood group))
Diseases named in the same sentence as ABCG2 in open-access papers (continued):
Sharing a sentence is not in itself a finding about the gene and the disease.
cancer (continued). "While further investigation is required to understand the mechanisms of acquired resistance in patients treated with furmonertinib, our results indicate that the overexpression of ABCB1 or ABCG2 is unlikely to play a significant role in the development of resistance to furmonertinib in cancer cells." (PMID 37762275, 2023). "Moreover, we demonstrated that hydroxygenkwanin reverses ABCG2-mediated MDR by modulating the drug efflux function of ABCG2, without altering its expression at the protein level in these cancer cells." (PMID 36361555, 2022). "Our results revealed that, although ensartinib could block P-gp-mediated drug efflux at higher concentrations, it could not resensitize P-gp- or ABCG2-overexpressing cancer cells to cytotoxic drugs at non-toxic low concentrations." (PMID 35565470, 2022). "In addition to ABCG2, APOE and LFER reportedly play a role in cancer stem cells." (PMID 35277124, 2022). "A literature search failed to retrieve any publication with a pan-cancer analysis for ABCG2." (PMID 36555598, 2022). "Similarly, ABCG2-mediated resistance to the ABCG2 drug substrates mitoxantrone, topotecan and SN-38 was not reversed by ensartinib in ABCG2-overexpressing S1-MI-80 or H460-MX20 cancer cell lines, or in the ABCG2-transfected R482-HEK293 cell line." (PMID 35565470, 2022). "ABCG2 is considered as a biomarker of cancer stem-like cells (CSCs), which can arise from various sources, including long-lived stem or progenitor cells or via dedifferentiation from non-stem cancer cells." (PMID 36555598, 2022). "Differing from bulk cancer cells, this liver cancer stem cell subpopulation displays resistance to traditional chemotherapeutic drugs via overexpression of the ATP-binding cassette transporters (i.e., ABCB1, ABCG2, and ABCC1), which serve as pumps to actively expel small molecular drugs." (PMID 36358973, 2022). "Our data show that hydroxygenkwanin did not significantly alter the protein expression of ABCG2 in NCI-H460/MX20 or A549-Bec150 cancer cells, thus suggesting that it restores the chemosensitivity of these multidrug-resistant cancer cells by attenuating the function of ABCG2." (PMID 36361555, 2022). "Through CRISPR/Cas9 gene editing, we recently reported that 110α and 110β subunits of the phosphoinositide 3-kinase (PI3K) signaling pathway are potential targets for reversal of ABCB1/P-gp- and ABCG2/BCRP-mediated cancer MDR in a manner independent of AKT expression." (PMID 35459184, 2022). "In addition, the protein and mRNA expression levels of USP6NL, pluripotency and cancer stem cell markers (CD44 and CD133), transcription factor (Nanog and SOX2), and efflux transporter ABCG2 were significantly overexpressed in the U87MG-R and T98G-R sphere compared with the parental control." (PMID 35884836, 2022). "Thus, if a role for ABCG2 in PpIX mediation seems clear, its expression level in the different cell lines do not explain PpIX selective accumulation in cancer cells after 5-ALA treatment." (PMID 35887311, 2022). "However, as TPT is a substrate of ABCG2, ABCG2-mediated drug exportation could induce TPT resistance in cancer cells, leading to failure in chemotherapy." (PMID 33829017, 2021). "From the cytotoxicity studies, 1 and 3 μM of GS-9973 were used for the reversal experiments in the ABCG2 overexpressing cell line as the cell survival fraction was around 85% after 72 h incubation in both the NCI-H460 parental and resistant NCI-H460/MX20 cancer cells." (PMID 34326700, 2021). "A promoter-based reporter for ABCG2 may also be not relevant in CSCs, as the expression of the molecule in cancer is mainly regulated by promoter demethylation." (PMID 34150761, 2021). "Moreover, our recent study demonstrated that the L7EB1/TPFPP/siABCG2-Lactosome particles, not only exhibited an ABCG2 gene silencing effect in the cytosol, but also mediated photo-induced cell death via the ALA-mediated PpIX accumulated PDT pathways in cancer cells." (PMID 33670777, 2021).
cancer (continued). "After USP24 knockdown, the levels of P-gp, ABCG2, and ezrin were decreased, which indicated that USP24 as a deubiquitinating enzyme may stabilize P-gp, ABCG2, and ezrin to enhance the ability of pumping out of a drug from cancer cells." (PMID 33846536, 2021). "The reversal effect of GS-9973 in NCI-H460/MX20 cancer cells could be a change in the subcellular localization of ABCG2 from the cell membrane (i.e., the transporter would not be in the cell membrane, producing a decrease in drug efflux from the cells)." (PMID 34326700, 2021). "In addition, RT-PCR (quantitative real-time PCR) experiments indicated that the incubation of NCI-H460/MX20 cancer cells with 3 μM of GS-9973 for 72 h did not change the level of ABCG2 mRNA expression." (PMID 34326700, 2021). "Moreover, the efficacy of the anticancer drug, cisplatin was not altered significantly by 3 μM of GS-9973 in the parental and resistant cancer cells proving that cisplatin is not an ABCG2 specific substrate which is consistent with the previous studies." (PMID 34326700, 2021). "Our data suggest that ABCG2 does not confer significant resistance to TP-3654 and may not play a major role in the induction of resistance to TP-3654 in cancer patients." (PMID 34502348, 2021). "Indeed, the ABCG2 and ABCB1 transporters play a major role in MDR-related cancers." (PMID 33158067, 2020). "ABCB1 (P-glycoprotein, P-gp; multidrug resistance 1, MDR1), ABCG2 (breast cancer resistance protein, BCRP; mitoxantrone resistance, MXR), and ABCC1 (multidrug resistance protein 1, MRP1) are the most important ABC transporters and the overexpression of them render emergence of MDR in cancer cells." (PMID 32984343, 2020). "Therefore, the EC16-1/saporin nanocomplex represents a novel anticancer strategy, not only for cancer patients with non-resistant tumor but also for patients with ABCB1 or ABCG2 drug-resistant cancers." (PMID 32098067, 2020). "In addition, in ABCG2 overexpressing cancer cells NCI-H460/MX20 cells, gleasatinib failed to reverse topotecan (an ABCG substrate) resistance." (PMID 31106148, 2019). "One cancer stem cell marker SOX2 was up-regulated in HOS-R/DOXO compared to its parental line (log2 FoldChange 1.89, adjusted p value 6,45×10-04), while none of the cancer stem cell markers (SOX2, OCT4, SSEA4, NANOG and ABCG2) were modified in MTX-resistant lines." (PMID 31319571, 2019). "Cancer stem cells (CSCs) were identified as a “side population” (SP) by flow cytometric analyses based on the efflux of Hoechst dye by the family of adenosine triphosphate (ATP)-binding cassette (ABC) drug transporters such as ABCB1 and ABCG2 present at the plasma membrane." (PMID 31867270, 2019). "ABCG2 correlates functionally with dye negative side population, a biomarker of cancer stem cells and was considered an interesting functional candidate in pAg presentation because of the known association with statins, cholesterol metabolism, and the HMG-CoA reductase pathway." (PMID 29670629, 2018). "Moreover, dacomitinib did not significantly alter anticancer activity of non-ABCG2 substrates on cancer cells." (PMID 29458405, 2018). "In addition, depletion of cellular ATP by AF could in turn compromise the drug efflux pump activity of ABCG2, leading to more intracellular retention of ADM in cancer cells." (PMID 29367724, 2018). "Therefore, we performed in vitro experiments to observe whether olmutinib could reverse MDR in cancer cells overexpressing ABCB1, ABCG2, or ABCC1 transporters." (PMID 30356705, 2018). "Therefore, we performed in vitro experiments to evaluate if olmutinib could reverse MDR in cancer cells overexpressing ABCB1, ABCG2, or ABCC1 transporters." (PMID 30356705, 2018). "In addition, expression of ABCG2 has been shown to correlate to cancer stem cells, explaining their unique ability to export Hoechst333342 dye out of the cells, creating a side population when using FACS to isolate cancer stem cells." (PMID 30555629, 2018).
cancer (continued). "To characterize whether cells that survived 5-FU exposure were related to the cancer stem phenotype, we compared gene expression of genes involved in cell survival (BAX and BCLL2) and drug resistance (ABCG2) among cells surviving 5-FU exposure and control cells." (PMID 28611669, 2017). "The resistant cell lines were analyzed for cross-resistance to other anti-cancer drugs, global gene expression, growth rates, TOP1 and TOP2A gene copy numbers and protein expression, and inhibition of the breast cancer resistance protein (ABCG2/BCRP) drug efflux pump." (PMID 26801902, 2016). "In our study, Western blot results showed that overexpression of NEK2A in cancer cells upregulated ABC transporter family members, including ABCB1 (p-glycoprotein, MDR1), the multidrug resistance protein ABCC1 (MRP1), and the breast cancer resistant protein ABCG2." (PMID 25705694, 2015). "ABCG2, the second member of the subfamily G of the human ABC transporter superfamily, has been detected in a large number of hematological malignancies and solid tumors, indicating that this transporter might play an important role in the MDR of cancers." (PMID 26575421, 2015). "The purpose of this study was to evaluate the effect of ABCG2 monoclonal antibody (McAb) combined with paclitaxel (PTX) conjugated with Fe3O4 nanoparticles (NPs) on MM progressed from cancer stem cells (CSCs)in non-obese-diabetic/severe-combined-immunodeficiency (NOD/SCID) mouse model." (PMID 26314844, 2015). "The finding that Ko143 was only able to enhance PpIX fluorescence and ALA-PDT response in two TNBC cell lines with increased ABCG2 transporter activity, but not in normal and other cancer cell lines without elevated ABCG2 activity, demonstrates the selectivity of this therapeutic enhancement." (PMID 26282350, 2015). "One of the main features of chemoresistant cancer cells is the high cell surface expression of ATP binding cassette (ABC) transporters, such as P-glycoprotein (Pgp/ABCB1), multidrug resistance (MDR) related proteins (MRPs/ABCCs) and breast cancer resistance protein (BCRP/ABCG2)." (PMID 25686827, 2015). "High expressions of ABCG2, ABCB1, or ABCC1 were validated in CSCs in various cancers, and the ability of CSCs to extrude Hochest 33342 by ABCG2 was used to develop the “side population” method, which is frequently used to isolate stem-like cells from primary tumors or cancer cell lines." (PMID 26431273, 2015). "Some groups have hypothesized that, although not all CSCs are ABCG2-positive, ABCG2-positive cancer cells with at least some stem-like qualities become more relevant during the development of treatment resistance." (PMID 26714461, 2015). "Several putative stem cell markers, such as CD44, CD24, CD166, EpCAM, ABCG2, CD133, and podoplanin, are commonly studied in identifying and isolating the CSCs from the solid tumors; however, subsequent studies demonstrated that the choice of CSC markers differs among cancer originations." (PMID 24804195, 2014). "Cancer stem cells (CSC), which express CD133, CD44, ATP-binding cassette sub-family G member 2 (ABCG2) and Aldehyde dehydrogenases (ALDH), are a subpopulation of tumor cells that display self-renewal and the ability to give rise to heterogeneous lineages of cancer cells." (PMID 25084809, 2014). "Alternatively, depletion of GIPC in cancer cells may result in the sequestering of ABCG2 in vesicles, rendering it inaccessible and therefore, nonfunctional." (PMID 25469510, 2014). "The ability of LMWH to sensitize SP cells to chemotherapy by inducing ABCG2 degradation through the proteasome pathway may provide an explanation for the unknown mechanism by which LMWH improves chemotherapy response and survival in cancer patients." (PMID 22844424, 2012).
cancer (continued). "Non-cancer cell types were represented by sorted CD26+ luminal epithelial, CD104+ basal epithelial, CD49a+ stromal smooth muscle, CD31+ endothelial cells, and prostate cell populations identified and isolated by their expression of the transmembrane ATP-binding cassette transporter ABCG2." (PMID 21605402, 2011). "Taken together, our results suggest that the inhibition of both ABCG2 and GADD45β might be used as a new target for curative therapy without recurrence or metastasis through the targeting of cancer stem-like cells, such as SP cells." (PMID 21048853, 2010). "Some key regulatory genes and proteins were modulated, such as ATP7A, ABCG2, ABCC1 and ABCB1 in response to EC-synthetic retinoids, suggesting that their expression may be under the regulation of retinoid signaling pathways with a potential role in diminishing cancer resistance and carcinogenesis." (PMID 36012706, 2022). "Moreover, our results indicate that ABCG2 does not mediate resistance to TP-3654 and may not play a major role in the induction of resistance to TP-3654 in cancer patients." (PMID 34502348, 2021). "In addition, midostaurin could not antagonize ABCG2-mediated MDR in ABCG2-overexpressing cancer cells NCI-H460/MX20." (PMID 31275850, 2019). "Here, we found that dacomitinib, an irreversible pan-ErbB tyrosine kinase inhibitor (TKI) in phase III clinical trial, could enhance the efficacy of conventional chemotherapeutic agents specifically in ABCG2-overexpressing MDR cancer cells but not in the parental sensitive cells." (PMID 29458405, 2018). "However, currently, there is no clinically approved ABCG2 modulator for treating MDR in cancers." (PMID 30181510, 2018). "Thus, we demonstrated that inhibition of ABCG2 in LPS-stimulated mDCs can potently induce tolerogenic potentials in these cells, providing crucial new information that could lead to development of better strategies to combat MDR cancer." (PMID 25111504, 2014). "Although in our EVs from eribulin-treated cancer cells, ABCC11 mRNA was not up-regulated, we found that both ABCC2 (log2FC = +4.570, about 23 times more) and ABCG2 (log2FC = +2.366, about 5 times more) were up-regulated." (PMID 38534323, 2024). "Our data suggest that furmonertinib was not efficiently effluxed out of cancer cells by ABCB1 and ABCG2." (PMID 37762275, 2023). "Also, the effect of MK-2206 on the ABCG2 ATPase was determined in High-five insect cells and not in cancer cells and thus, it is possible that the effect of MK-2206 on ABCG2 ATPase in cancer cells may be different from that of the High-five insect cells, although this remains to be determined." (PMID 37521473, 2023). "In previous reports, Wnt5a induce EMT and potentiate metastasis across multiple cancer types through non-canonical mechanisms and also mediate gemcitabine resistance in PDAC via upregulation of ABCG2." (PMID 34794402, 2021). "The EC16-1/saporin complex induces apoptosis in the parental cancer cells and in the resistant ABCB1- and ABCG2-overexpressing cells and does not significantly alter the intracellular localization of ABCB1 or ABCG2." (PMID 32098067, 2020). "We then demonstrated that TMP195 enhances drug-induced apoptosis of multidrug-resistant cancer cells by modulating the drug transport function of ABCB1 and ABCG2, without affecting the protein expression of either transporter." (PMID 31905792, 2019). "Numerous reports show that in most cancer cases that do not respond to therapy, an abundant expression of ABCB1, ABCC1, or ABCG2 appears as poor prognostic factor." (PMID 28623509, 2017). "In the present study, we showed that trametinib significantly potentiated the effects of vincristine and doxorubicin on inhibition of growth, arrest of cell cycle and induction of apoptosis in cancer cells overexpressed ABCB1, but not ABCC1 and ABCG2." (PMID 25915534, 2015).
cancer (continued). "Trametinib significantly potentiated the effects of two ABCB1 substrates vincristine and doxorubicin on inhibition of growth, arrest of cell cycle and induction of apoptosis in cancer cells overexpressed ABCB1, but not ABCC1 and ABCG2." (PMID 25915534, 2015). "Although such heterogeneity has been described previously, ABCG2- and ABCB1-expressing cancer cells have never been systematically compared on the functional level." (PMID 25216521, 2014). "Studies with ABC transporter-overexpressing carcinoma cell models confirmed that nilotinib effectively reversed ABCB1- and ABCG2-mediated drug resistance, while showed no significant reversal effect on ABCC1- and ABCC4-mediated drug resistance." (PMID 24651611, 2014). "In conclusion, our studies showed that 5% ethanol decreased ABCG2 protein function and 5% ethanol–DDP induced apoptosis of lung SP cells plus non-SP cancer cells in vitro and DDP-resistant lung tumor cells in vivo." (PMID 24009622, 2013). "To prove this point we sort cancer cells according to a putative CSC marker, ABCG2, and show that senescence is more prevalent for negative cells, suggesting that CSC are able to rejuvenate an otherwise senescent cell population." (PMID 22275856, 2012). "Our findings indicate that treatment with furmonertinib at concentrations ranging from 50 nM to 500 nM did not produce a significant impact on the protein expression of ABCB1 in NCI-ADR-RES and KB-V1 cells, nor on ABCG2 in S1-MI-80 and H460-MX20 cancer cells over a period of 72 h." (PMID 37762275, 2023). "Overexpression of the ABC transporters, ABCB1 and ABCG2, are two of the major mediators of MDR in cancer, and antagonists targeting ABCB1 and ABCG2 have undergone clinical Antagonists targeting ABCB1 and ABCG2 have been clinically evaluated; unfortunately, none have been clinically approved." (PMID 38169723, 2023). "Furthermore, RuZ had a low affinity for ABCG2 and ABCB1, thus, indicating that RuZ is not extruded from MDA-MB-231 cancer cells." (PMID 37408573, 2023). "In contrast, the protein expression of ABCB1 and ABCG2 in multidrug-resistant cancer cells was unaffected by TMP195 for 72 h, indicating that the downregulation of ABCB1 or ABCG2 does not play a significant role in the chemosensitization of multidrug-resistant cancer cells by TMP195." (PMID 31905792, 2019). "Moreover, there was no significant alteration of insensitivity of cancer cells to cisplatin, which was neither an ABCB1 nor ABCG2 substrate." (PMID 30425643, 2018). "In addition, there was no significant alteration insensitivity of cancer cells to compounds that were not ABCB1 or ABCG2 substrates, which suggests that the efficacy of osimertinib to reverse MDR is specific to ABCB1 and ABCG2." (PMID 27649127, 2016). "Furthermore, the ATPase activity of ABCG2 and P-gp was stimulated by lazertinib; however, their mRNA expression or protein expression levels were not affected by lazertinib treatment in the MDR cells nor their plasma membrane localization in cancer cells." (PMID 38269272, 2023). "Therefore, this study investigates whether 5% ethanol could inhibit ABCG2 and DDP in 5% ethanol could kill lung SP plus non-SP cancer cells in vitro as well as its effects on DDP-resistant tumors in vivo." (PMID 24009622, 2013).